IL4R (interleukin 4 receptor)
Diseases named in the same sentence as IL4R in open-access papers (continued):
Sharing a sentence is not in itself a finding about the gene and the disease.
infection (continued). "The other strains kept the infection for 50 days (IL-5-/- KO), 40 days (IFN-γ-/-/IL-5-/- DKO), 20 days (IFN-γ-/- KO) and 5 days (IL-4R-/- KO)." (PMID 22348321, 2012). "It is possible that functional cooperation between IL-4Rα/STAT6 and additional pathways promotes maximal Arg1 expression in alveolar macrophages after infection with A. fumigatus." (PMID 21246055, 2011). "In the same study, infection of moMΦ with Georgia 2007 strain down-regulated other receptors, such as interferon receptors (IFNAR1, IFNAR2, IFNGR) and interleukin receptors (IL4R, IL10RA, IL10RB, and IL17RA), as well as transcriptomic factors (e.g., FOS, JUN, and TBK1)." (PMID 40530033, 2025). "Flow cytometry analyses of myeloid cells showed the recruitment at the site of infection of Ly6G+, Ly6Chi, and Ly6Clow cells in the absence of IL-4Rα." (PMID 38392907, 2024). "We have previously observed an upregulation of the gene encoding IL-4 in BALB/c resident peritoneal macrophages in response to infection with L. panamensis, but no changes were found in IL-4Rα expression levels." (PMID 39830895, 2024). "The elevated specific IgG occurred late during infection and corresponded with the time points at which P. murina lung burden was at the limit of detection in the IL-4Rα−/− pups but not in the wild type pups." (PMID 34682248, 2021). "Importantly, the IL-4 environment can also significantly impact the quality/avidity of T cell immunity, where IL-4R⍺ expression was inversely related to IFN-γ and TNF expression on effector T cells following infection/vaccination." (PMID 34006897, 2021). "More recently, in the absence of any infection, IL4Rα -independent pathways of Ym1 and RELMα expression have been described in lung macrophages." (PMID 34329367, 2021). "Our data demonstrate multiplicity of Th2-cytokine control of eosinophil tissue recruitment during chronic filarial infection and that IL-4R–independent/IL-5– and CCR3-dependent pathways are sufficient to control filarial adult infection via an eosinophil-dependent effector response prior to patency." (PMID 32571840, 2020). "So far we have ruled out a protective role in VL for IL-4Rα responsiveness on neutrophils and macrophages in primary infection and chemotherapy, and herein T cells during primary infection." (PMID 31475014, 2019). "IL4R/GPIbα mice had no GPIbα expression (P < .001 vs controls) and reduced platelet counts during infection (P < .01 vs controls)." (PMID 30312422, 2019). "Our analysis suggested only a transient and tissue specific impact on disease course due to lack of IL-4Rα on T cells, limited to a reduced hepatic parasite burden at day 30 post-infection." (PMID 31475014, 2019). "Altogether, this strengthens and confirms previous data, in which CD11c-expressing cells served as a reservoir for pathogen replication, and showed increased infection in the absence of IL-4-signaling via the IL-4Rα chain." (PMID 32039054, 2019). "Together, these data indicate that IFN-γ-responses in LckcreIL-4Rα−/lox mice developed fully in the absence of IL-4Rα+ signaling on CD4+ T cells when compared with wild-type mice over the course of infection." (PMID 31475014, 2019). "A significant number of studies from our laboratories have identified protective roles for IL-4, IL-13 and IL-4Rα signaling, not merely during primary infection with L. donovani infection, but also for effective sodium stibogluconate chemotherapy." (PMID 31475014, 2019). "IL4R/GPIbα mice showed increased bacterial burden in the lung after 3 days of infection, but not to the extent of that in platelet-depleted mice." (PMID 30312422, 2019). "Both global IL-4Rα−/− BALB/c and C57BL/6 mouse groups had significantly smaller lesion diameters in the ears and significantly lower parasite loads in the ear than littermate control IL-4Rα−/lox BALB/c mice after L. major LV39 infection." (PMID 30275010, 2018).
infection (continued). "Post-infection, the CCR3 ligand, CCL11, was upregulated at the transcript level in peritoneal cells and relative transcripts were significantly impaired in BmL3-infected IL-4Rα-/- mice." (PMID 29547639, 2018). "Nonetheless, for both proteins there were significant increases in expression during infection independent of IL-4Rα signaling." (PMID 30500858, 2018). "Infection with L. major LV39 resulted in similar ear lesion diameters and cervical lymph node parasite loads between KRT14cre IL-4Rα−/lox BALB/c and littermate control IL-4Rα−/lox BALB/c mice, with the surprising exception of significantly reduced parasite loads in the ear." (PMID 30275010, 2018). "Subcutaneous infection of L. major IL-81 or LV39 in the footpad of KRT14cre IL-4Rα−/lox BALB/c mice revealed no role for IL-4Rα-responsive keratinocytes in modulating nonhealing disease to L. major." (PMID 30275010, 2018). "After infection with L. major IL-81, parasite loads of global IL-4Rα−/− BALB/c mice in the footpad, popliteal lymph node, and spleen appeared to be significantly lower than the loads in littermate control IL-4Rα−/lox BALB/c mice." (PMID 30275010, 2018). "Mice lacking IL-4Rα expressing B cells had significantly enlarged granulomas in the liver at both 16 and 24 weeks post-infection compared to littermate control mice." (PMID 30619289, 2018). "Global IL-4Rα−/− BALB/c mice, which are generally resistant to L. major infection, had significantly less footpad swelling than littermate control IL-4Rα−/lox BALB/c mice during infection with either strain." (PMID 30275010, 2018). "Moreover, the default Th2/type 2-driven cellular and humoral immune response characteristic of BALB/c mice, developed independently of IL-4Rα-responsive keratinocytes following L. major LV39 and IL81 infection in the footpad (submitted manuscript)." (PMID 29176972, 2017). "Taken together, the present data rule out a major role for skin IL-4 and keratinocyte IL-4Rα signaling in the development of a Th1 protective immune response following experimental infection with L. major." (PMID 29067025, 2017). "Following infection with L. major (LV39), IL-4−/− or IL-4Rα−/− mice on a BALB/c genetic background were able to control lesion size and the levels of IFNγ present in draining lymph node (dLN) cells was either very low or remained unchanged compared to that observed in BALB/c wild-type mice." (PMID 29067025, 2017). "This conclusion adds to previous findings that have made use of IL-4Rα-/- mice where IL-4Rα is already absent during the primary infection." (PMID 28651009, 2017). "Whilst the absence of IL-4Rα did not have an impact on inflammation at the skin site of infection, nor on the number of DEC, its absence significantly increased the numbers of cells expressing high levels of MHC-II." (PMID 27505056, 2016). "Taken together, these data demonstrate that the absence of IL-4Rα-dependent macrophages did not influence the survival and immune response to high dose infection with H37Rv." (PMID 25790379, 2015). "Therefore, we measured the expression of IL4Rα (receptor) on CD4+ T cells by flow cytometry and IL13 (ligand) expression in the lung by real-time PCR during primary infection." (PMID 26231396, 2015). "Next we investigated whether IL-4Rα levels on CD8+ T cells were fixed/unchanged, or responsive to IL-4 during infection." (PMID 23383283, 2013). "L. major studies demonstrated hypersusceptibility to infection and strikingly increased parasite loads in peripheral organs of mice lacking IL-4Rα on DCs." (PMID 24204259, 2013). "In addition, except for 4 of the regulatory genes (IRF4, JAK1, NFATC4 and STAT6), many of the other genes in this pathway were only transiently expressed at 2 (IL4R and PTPRC) or 4 and/or 8 (IL13, IL4 and CEBPB) weeks post-infection." (PMID 23448601, 2013).
infection (continued). "For example, disruption of IL-4Rα expression on CD4+ T-cells results in a significantly reduced TH2 response to primary N. brasiliensis infection and contributes to optimal control of secondary infection." (PMID 24204255, 2013). "In contrast, immunization with conditioned IL-4Rα−/− BMDC was not capable to induce the control of infection, as indicated by uncontrolled lesion development and parasite burden at the site of infection." (PMID 22802978, 2012). "With the exception of IL-4R-/- KO mice that kept the infection only for a few days (data not included in statistics below), larvae increased significantly (p < 0.001) in length and width with time." (PMID 22348321, 2012). "As previously shown, infection with N. brasiliensis enhanced tension to acetylcholine significantly in IL-4Rα-responsive control mice when compared to non-infected control mice." (PMID 23284939, 2012). "Following infection (day 7 and 10) contractile responses significantly increased in control mice but not global IL-4Rα−/− mice." (PMID 23284939, 2012). "As previously demonstrated, IL-4Rα−/− mice did not clear infection efficiently showing a maintained egg production at day 11 PI and the presence of adult worms detected at day 10 PI." (PMID 23284939, 2012). "Further studies demonstrated that the close similarities in the disease phenotypes of LysMCreIL-4Rα−/lox and IL-4Rα−/lox mice were independent of site, dose of inoculum, and life cycle stage initiating infection (data not shown)." (PMID 21245915, 2011). "However, the IL-4Rα-infected mice exhibited the highest count for the WBC, although not significant, this could be due to the inhibition of IL-4R and the burden of infection." (PMID 40977748, 2025). "However, expression of Alox12, Alox12e, Alox8, Alox12b, Il13rα1, Il4rα, Il2rg, and Il13 were not altered following Hpb infection." (PMID 40490052, 2025). "We investigated whether the absence of IL-4Rα on Foxp3 Treg cells influenced the lung cytokine profile in tissue homogenates at 3 and 18 weeks post-infection (wpi)." (PMID 39483462, 2024). "Interestingly, the LysMcreIL-4Rα−/lox (cre/LoxP) mice, whose macrophages have a lineage-specific IL-4Rα absence, showed low or no parasite load, with the infection being resolved in 88% of the mice as early as four weeks after infection." (PMID 38392907, 2024). "Finally, we did not thoroughly explore the effects of heterologous infection and LysMCre IL-4R KO on viral copy number." (PMID 36032072, 2022). "Similarly, the majority of IL-4Rα−/− mice (6/9) were infection negative, and levels of surviving adults were significantly reduced compared with larval burdens at 2 wk or adult loads at 5 wk (median yield of 0 versus 22 B." (PMID 32571840, 2020). "In the current study, we explored the long-term consequences of IL-4Rα deficiency and degree of eosinophil recruitment on B. malayi filarial parasitism using a typically nonpermissive BALB/c mouse model of infection and additional IL-5 and CCR3 compound deficiencies." (PMID 32571840, 2020). "In contrast, no serum IgE was detected for global IL-4Rα−/− mice any day post-infection." (PMID 31475014, 2019). "Taken together, these data suggest that IL-4Rα might play a role in regulation of DC maturation at the later stages of infection, but is not required for T cell activation in the lesion-draining lymph node." (PMID 32039054, 2019). "Early in infection, levels of Ym1 were independent of IL-4Rα-signaling." (PMID 30500858, 2018). "Together, these findings highlight that during intradermal infection in the ear, IL-4Rα signaling on keratinocytes in BALB/c mice does not affect protective immune responses, as determined by cellular responses, cytokine production, and type 1 and type 2 antibody titers." (PMID 30275010, 2018).
infection (continued). "Interestingly, although the levels of serum IL-4 were significantly reduced in infected mb1creIL-4Rα−/lox mice at 16 weeks post-infection, the levels of IL-4 were almost 3-fold higher in mice lacking IL-4Rα expressing B cells at 24 weeks post-infection." (PMID 30619289, 2018). "However, upon infection of both strains almost all MΦ regardless of phenotype expressed RELMα, a reflection of the ability of IL-4Rα signaling to induce RELMα expression independent of strain or origin." (PMID 29299998, 2018). "In addition, total lack of IL-4Rα signaling did not have an impact on the resolution of the infection." (PMID 29067025, 2017). "Therefore, we postulated that the absence of IL-4Rα-responsive macrophages at the site of infection would induce signals that lead to a polarized protective Th1 response due to the absence of alternatively activated macrophages." (PMID 29176972, 2017). "However, here, we show that irrespective of the site of infection, the absence of IL-4Rα on keratinocytes in L. major-infected mice did not have any impact on lesion development and immune response." (PMID 29067025, 2017). "Surprisingly, mice deficient in IL-4Rα expression show significantly higher lung burdens at early time points after infection (i.e. 7 and 14 dpi) but not at later time points (i.e. 21 and 42 dpi), when the IL-4Rα−/− mice exhibit significantly lower fungal burdens in the lung." (PMID 24475277, 2014). "Of note, IL-4Rα−/− mice failed to accumulate the large numbers of macrophages that were observed in the granuloma of wildtype mice, indicating that IL-4Rα signaling is necessary for the recruitment and/or expansion of macrophages at the site of infection." (PMID 24244174, 2013). "Protection against secondary infection depended on IL-4Rα and IL-13; but not IL-4." (PMID 24204255, 2013). "CD4+ T cell specific (LckcreIL-4Rα−/lox) IL-4Rα−/− mice are more resistant than global IL-4Rα−/− mice to infection with L. major, indicating that in the absence of a polarized Th2 response, there is a role for an IL-4/IL-13 responsive non-CD4+ T cell in early resistance to infection." (PMID 21245915, 2011). "To conclude in this study utilising tissue specific IL-4Rα−/− mice we demonstrate that upon infection with L. mexicana initial lesion growth is dependent on a non-CD4+ T cell population responsive to IL-4/IL-13, while progressive infection is dependent on CD4+ T cells responsive to IL-4." (PMID 21245915, 2011). "However, infection with the nematode S. obvelata did not increase goblet cell hyperplasia in the host colon, irrespective of IL-4Rα expression." (PMID 18373844, 2008). "However the role of IL-4Rα in goblet cell hyperplasia in the intestine during the live infection has not been shown." (PMID 18373844, 2008). "Consequently, in this study we generated CD4+ T cell-specific IL-4Rα−/− (LckcreIL-4Rα−/lox) mice and iLckcreIL-4Rα−/lox mice that lack IL-4Rα on both CD4 and CD8 T cells to determine the temporal role of IL-4 signaling via CD4+ and CD8+ T cells on the progression of VL infection." (PMID 31475014, 2019). "Interestingly, however, IL-4Rα knockdown did not prevent the recall of a strong type 2 response as judged by IL-4 levels and the considerable reduction of the number of remnant worms in the gut of IL-4Rα knockdown mice during secondary infections." (PMID 28651009, 2017). "Thus, vaccinated IL-4Rα-/- mice fail to expel worms and actually incurred higher egg burdens than wild-type controls, despite generating HES-specific IgG1 responses similar in titre to those seen in B6 primary infection, and equivalent in specificity to immunised wild-type mice." (PMID 25816012, 2015). "Consistent with the reduced transcription of IFN-γ in the absence of IL-4Rα signaling, lower levels of this cytokine are detectable upon ex vivo antigen-specific re-stimulation of lung leukocytes at early (i.e. 7 dpi) but not late (i.e. 42 dpi) time points of infection (data not shown)." (PMID 24475277, 2014).
infection (continued). "At later time-points (week 4 post-infection), MHCII expression was lower in the absence of IL-4Rα on DCs whilst CD80 expression was similar between CD11ccreIL-4Rα−/lox and littermate control mice." (PMID 32039054, 2019). "However, because Mφ alternative activation can occur independently of IL4R via FcR ligation or other polarising signals such as IL-33, we do not rule out a role for Mφ alternative activation signals being triggered by non-lymphocyte, IL-4 responsive cell types in our infection system." (PMID 29547639, 2018). "This showed that the absence of either IL-4Rα, or RELMα, leads to increased number of CD4+ T cells in the sdLN following repeated infection comparable to the levels seen in 1x mice." (PMID 27505056, 2016). "At day 3 post-infection, CD11b+ DCs from CD11ccreIL-4Rα−/lox and littermate control mice showed equivalent expression of MHCII and CD80, demonstrating that early activation of DCs was unaltered in the absence of IL-4Rα expression." (PMID 32039054, 2019). "Unlike global IL-4Rα−/− mice infected with L. donovani that developed significantly higher parasite burdens than wild-type mice in this and previous studies, CD4+ T cell specific IL-4Rα−/− mice were by comparison resistant to infection." (PMID 31475014, 2019). "The lack of impact of IL-4Rα signaling on lesion development, parasite control, and the differentiation of CD4+ Th1 cells at the site of infection and in the dLN firmly demonstrated that IL-4 signaling on keratinocytes was not involved in Th1 cell differentiation following L. major infection." (PMID 29067025, 2017). "In the absence of IL-4Rα-responsive keratinocytes, C57BL/6 mice controlled the development of inflammatory lesions upon infection with L. major LV39 and IL-81, which correlated with reduced parasite burdens and the expansion of Th1/type 1 cellular and humoral immune responses." (PMID 29176972, 2017). "Interestingly, at 24 h post infection there was no further increase in immune responsive genes but down-regulation of STAT4, TNFR, IL4R, and TNF6 genes were found." (PMID 21439068, 2011). "Previous studies infecting global IL-4Rα−/−, IL-4−/−, and IL-13−/−mice on a BALB/c background with the visceralizing parasite Leishmania donovani have shown that the T helper 2 cytokines, IL-4, and IL-13, play influential but not completely overlapping roles in controlling primary infection." (PMID 31475014, 2019).